IL1B (interleukin 1 beta)
Diseases named in the same sentence as IL1B in open-access papers (continued):
Sharing a sentence is not in itself a finding about the gene and the disease.
osteoarthritis (continued). "Our previous studies suggested that cytokines (e.g., IL-1β, IL-6, and TNF-α) expressed in articular chondrocytes during the pathogenesis of osteoarthritis and RA increase HIF-2α expression and protein accumulation under normoxia." (PMID 31098335, 2019). "All these results indicate that OA inducers, including IL-1β, TNF-α, and H2O2 can promote progression of osteoarthritis in different ways." (PMID 31772142, 2019). "Taken together, hyperacute serum can be a promising blood separation product in degenerative joint diseases, which enhances cell proliferation, the production of COL1A1 and osteonectin, while decreasing the level of RANKL, IL-1β, IL-6Rα, IL-12, and TNF-α." (PMID 31382623, 2019). "Some studies showed that IL-1β and TNF-α contributed to the pathogenesis of osteoarthrosis and induced the inflammation and destruction of the joints." (PMID 32083119, 2019). "In vivo study confirmed that DAS protected the cartilage in the development of osteoarthritis by inhibiting the expression of MMP-1, MMP-3, MMP-13, and IL-1β as well as enhancing the production of collagen II." (PMID 29370858, 2018). "The verification result showed that the expression levels of IL6, VEGFA, JUN, IL-1β, and ATF3 were significantly increased in osteoarthritis samples (p < 0.05)." (PMID 30186872, 2018). "Modulation of miR-448 efficiently affected IL-1β-stimulated degradation and synthesis of ECM in osteoarthritis chondrocytes." (PMID 29483929, 2018). "The serum concentrations of IL-1β were significantly attenuated by the combined treatment with Hévíz water and mud compared to the control mice in MIA-evoked osteoarthritis model." (PMID 30224931, 2018). "It has also been reported that chondrocytes and synovial cells from osteoarthritis patients, when cultured on collagen-PVP composites, showed proliferation and the suppression of IL-1β and TNF-α51." (PMID 29674743, 2018). "Interleukin 1 beta (IL1β) and Wingless-Type MMTV Integration Site Family (WNT) signaling are major players in Osteoarthritis (OA) pathogenesis." (PMID 29165387, 2017). "Inflammatory cytokines, including IL-1β and TNF-α, downregulate mir-140 expression leading to the development of osteoarthritis, most likely due to accelerated inflammation and/or ADAMTS5 activation." (PMID 28099924, 2017). "The roles of recombinant IL-1β and TNF-α in osteoarthritis are well elucidated in in vitro and in vivo studies." (PMID 28036032, 2016). "On the other hand, in primary human chondrocytes and osteoarthritis cartilage, S1P2 counteracted the pro-inflammatory signaling of IL-1β, including IL-1β-induced upregulation of inducible NO synthase." (PMID 27445808, 2016). "In fact the changes in ECM composition may play an important role in maintaining osteoarthritis damage and the alterations in hyaluronate degradation can be an alternative mechanism for the regulation of proteoglycan release from cartilage following IL1β stimulation." (PMID 26480822, 2015). "Following activation with IL-1β, human chondrocytes (normal human articulocytes from knee, NHAC-kn) expressed various pathophysiological markers of osteoarthritis (OA) and enzymes that degrade the extracellular matrix (ECM)." (PMID 26301248, 2015). "These degrading enzymes are regulated inter alia by inflammatory mediators, like IL-1β and TNF-α, which are closely related to matrix breakdown and which also play a significant role in degenerative disease, like osteoarthritis." (PMID 25822615, 2015). "In the presence of IL-1β, HMGB1 enhanced the phosphorylated p38 MAPK level and significantly potentiated NF-κB activation in SF from patients with osteoarthritis." (PMID 24302816, 2013). "Interleukin 1β (IL-1β) and tumor necrosis factor α (TNF-α) are key cytokines that drive the production of inflammatory mediators and matrix-degrading enzymes in osteoarthritis (OA)." (PMID 22605974, 2012). "TNFα, IL-1β and other pro-inflammatory cytokines can upregulate NOS in chondrocytes and synovial cells of osteoarthritis." (PMID 22479635, 2012).
osteoarthritis (continued). "Our results demonstrate that the signaling through TLR-4 is a proinflammatory mechanism in osteoarthritis that drives the upregulation of MMP-3, IL-1β, and TNF-α gene expression, leading to cartilage degradation and inflammation." (PMID 23118784, 2012). "For instance, TA could reduce the cytokine expression of IL6, IL1β, and TNFα in BV2 microglial cells, human osteoarthritis chondrocytes, in mouse models of ulcers and IL1β in BMDMs." (PMID 40565042, 2025). "Moreover, a strong correlation was observed between synovial fluid and synovial tissue concentrations of IL-1β, IL-10, and TNF-α in degenerative joint disease." (PMID 40649748, 2025). "Pro-inflammatorycytokines (IL-1β, IL-6, and TNF-α) and anti-inflammatorycytokine (IL-2) levels in mouse models of osteoarthritis were evaluated,resulting in a reduction of serum expression of pro-inflammatory cytokinesand an enhancement of anti-inflammatory activity." (PMID 40300853, 2025). "Research indicates that DMT1 is critical in the progression of osteoarthritis (OA) driven by iron overload; inhibiting DMT1 alleviates IL-1β-induced inflammatory responses and extracellular matrix degradation by significantly suppressing the MAPK and PI3K/AKT/NF-κB signaling pathways." (PMID 39744014, 2024). "In conclusion, l-carnitine augmented the probenecid’s anti-inflammatory effect to attenuate MIA-induced osteoarthritis in rats by provoking the miRNA-373 level and inhibiting the P2X7/NLRP3/NF-κB milieu, leading to the suppression of serum inflammatory cytokines: IL-1β, IL-18, IL-6, and TNF-α." (PMID 37994991, 2024). "Indeed, studies have identified NF-κB as abnormally activated in osteoarthritis, and several studies have demonstrated that the increase in MMP-13 expression after IL-1β was dependent of the activation of this transcription factor." (PMID 38543230, 2024). "Treatment with BAC protects against IL-1β-induced inflammation in chondrocytes by elevating the expression of IL-11 through activating AP-1 transcriptional activity, indicating the therapeutic potential of BAC in patients with osteoarthritis." (PMID 38983788, 2024). "Previous research has substantiated the anti-osteoarthritis efficacy of FJH-UBS, a derivative of Boswellia serrata gum resin enriched in KBA and AKBA, in interleukin (IL)-1β-stimulated human SW1353 chondrocytes and osteoarthritis-induced animal models of osteoarthritis." (PMID 38542192, 2024). "To prove this hypothesis, we explored the effects ALA‐24A on extracellular matrix (ECM) degradation, inflammation as well as oxidative stress using IL‐1β‐stimulated chondrocyte model and monosodium iodoacetate (MIA)‐induced rat osteoarthritis model." (PMID 37249294, 2023). "Despite the fact that predominant pro-inflammatory cytokines such as IL-1β, TNF-α, IL-15, or IL-6 are well described in human medicine research, it is not documented which biomarker is the gold standard for evaluating osteoarthritis in animal species." (PMID 37443993, 2023). "In addition, we demonstrated this pattern in human osteoarthritis chondrocytes stimulated with IL-1β; that is, the p-PI3K level was high in osteoarthritis chondrocytes." (PMID 38049841, 2023). "In a model of IL-1β-induced murine osteoarthritis, SOX11 was significantly down-regulated by IL-1β in chondrocytes, whereas TsI treatment reversed this down-regulation and protected chondrocytes from IL-1β-induced apoptosis." (PMID 37391758, 2023). "Induction of an osteoarthritis-like phenotype in the ATDC5 chondrocytes was confirmed by a significant upregulation of il6, mmp13, and colx10a1 and a decrease in col2a1 and acan expression following treatment with IL-1β." (PMID 36814717, 2023). "Daphnoretin can suppress IL-1β-induced chondrocyte apoptosis by inhibiting endoplasmic reticulum stress and NOD-, LRR- and pyrin domain-containing protein 3 (NLRP3) inflammasome activation and suppressing osteoarthritis." (PMID 37621874, 2023).
osteoarthritis (continued). "Human osteoarthritis chondrocytes can be inhibited by senegenin by inhibiting PI3K/AKT/NF-κB signaling pathway, inhibiting the expression of MMP-1, MMP-3, and MMP-13 induced by IL-1β, and the production of NO and PGE2 was reduced in human osteoarthritis chondrocytes." (PMID 35924058, 2022). "The effects of TIMPs as well as IL-1β, COX2 and other pro-inflammatory signaling molecules might be reversed by tSVF and could possibly slow down the progression of osteoarthritis in the affected joints, thereby reducing pain." (PMID 35892757, 2022). "As for osteoarthritis and DM, the top 5 most related genes were INS, TNF, IL-6, CRP, and IL-1B." (PMID 35719662, 2022). "IL-1β and TNF-α in patients with osteoarthritis can induce and obviously upregulate the expression of CRT in articular chondroblasts or synovial fibroblasts, CRTAC1 can be used as a biomarker to distinguish chondrocytes from osteoblasts and mesenchymal stem cells." (PMID 36507532, 2022). "In the pathogenesis of osteoarthritis (OA) disease, an important role was found for the pro-inflammatory cytokine IL1B, and a negative correlation between miR-144-3p and IL1B expression was also observed in OA." (PMID 36686646, 2022). "What is more, the expression of ADAMTS4 genes in the culture of synoviocytes from synovial tissues obtained from patients with osteoarthritis was significantly inhibited by ETA, and much more strongly inhibited when the TNF-α inhibitor was combined with a neutralizing anti-IL-1β antibody." (PMID 35407621, 2022). "One limitation of this study is that we only investigated the effect of FA on IL‐1β‐induced toxicity in osteoarthritis chondrocytes but did not isolate chondrocytes from healthy individuals or patients in the early stage of osteoarthritis." (PMID 34078001, 2021). "For example, non-virus-mediated interleukin-1β (IL-1β) short hairpin RNA (shRNA) were orally delivered via yeast microcapsules in mice to mitigate progression of osteoarthritis." (PMID 34592900, 2021). "Our findings suggest that SIRT1 activity is involved in mediating the protective effects of FA against IL‐1β‐induced toxicity and inhibition of SIRT1 by Sirtinol significantly attenuated the suppressive effects on IL‐1β‐induced osteoarthritis chondrocyte degeneration." (PMID 34078001, 2021). "In addition, allicin ameliorates the progression of osteoarthritis by decreasing TNF-α, IL-6, and IL-1β in chondrocytes." (PMID 34445305, 2021). "The phosphorylation of NR4A1 was increased in human osteoarthritis cartilage, and p38 inhibitor SB203580, JNK inhibitor SP600125 and ERK inhibitor FR180204 could significantly inhibited IL-1β induced NR4A1 phosphorylation." (PMID 32258036, 2020). "Pro-inflammatory cytokines including IL-1β and TNF-α play an important role in osteoarthritis." (PMID 33233504, 2020). "Furthermore, the mRNA expression of inflammatory mediators COX-2, IL-1β, TNF-α, and NF-κB was significantly decreased in the FJH-KO supplemented rats compared with that in rats with MIA induced osteoarthritis (p < 0.05)." (PMID 33233504, 2020). "The serum PGE2, IL-1β, IL-6, and TNF-α levels were higher in rats with MIA induced osteoarthritis; however, these levels were suppressed in FJH-KO supplemented rats with MIA-induced osteoarthritis compared with those in rats with MIA-induced osteoarthritis (p < 0.05)." (PMID 33233504, 2020). "In vitro overexpression and knockdown experiments demonstrated that NR4A1 could inhibit the p65 transcriptional ability and prevent the IL-1β induced MMPs expression in chondrocytes, thus indicating a protective role of NR4A1 in osteoarthritis." (PMID 32258036, 2020). "Remarkably, i-PRF addition to IL-1β-conditioned cultures has been shown to be superior to PRP treatment in modulating the inflammatory environment, by up-regulating the expression of pro-regenerative genes and down-regulating osteoarthritis-related markers." (PMID 30959772, 2019).
osteoarthritis (continued). "Interleukin-1 beta promotes multiple inflammatory mediators including nitric oxide, PGE2, chemokines, adhesion molecules, matrix metalloproteinases, and multiple cytokines leading to synovitis, cartilage destruction and ultimately osteoarthritis." (PMID 30234134, 2018). "We investigated the effects of SSa on IL-1β-induced NO and PGE2 production to test whether SSa exhibited anti-inflammatory effects in human osteoarthritis chondrocytes." (PMID 29179489, 2017). "Osteoarthritis is a multi-factorial disease process driven by the master regulators of cellular/ECM destruction, IL-1β and TNFα, pro-inflammatory molecules such as the COX-2-dependent cartilage-destructive enzyme prostaglandin E2 (PGE2), IL-6, IL-8, and the ECM-degrading enzymes such as the MMPs." (PMID 27255741, 2016). "Increased interleukin 1 beta (IL-1ß), interleukin 6 (IL-6), tumor necrosis factor-alpha (TNF-α) and prostaglandin E2 (PGE2) levels in synovial fluid are seen in internal derangements of TMJ such as anterior disc displacement and osteoarthritis." (PMID 25662545, 2015). "It is thought that IL1-β and TNF-α play an important role in the development of osteoarthritis." (PMID 25822615, 2015). "Our previous in vitro data on WIN-34B has shown cartilage protective effects through the regulation of matrix proteinases (aggrecanases and MMPs/TIMPs), inflammatory mediators (PGE2, NO, IL-1β, and TNF-α), and the MAPK pathways in osteoarthritis human cartilage explants culture and chondrocytes." (PMID 23983790, 2013). "Although IL-1β is believed to be crucial in the pathogenesis of osteoarthritis (OA), the IL-1β blockade brings no therapeutic benefit in human OA and results in OA aggravation in several animal models." (PMID 24238405, 2013). "Furthermore, the influence of IL-1β and TNF-α as the major pro-inflammatory cytokines released within the joint after trauma and involved in the initiation and progression of degenerative joint disease was investigated." (PMID 24034344, 2013). "We identified that PPARA, BMP7, IL1B, LEP, ITGA5 and SREBP1 protein levels in osteoarthritic chondrocytes were highly correlated with BMI, suggesting the potential role of metabolic-related proteins in the development of osteoarthritis." (PMID 19011694, 2008). "They suggest, however, that the potential benefit of glucosamine in osteoarthritis is not related to cartilage matrix biosynthesis, but is more probably related to its ability to globally inhibit the deleterious effects of IL-1β signaling." (PMID 17109745, 2006). "Indeed, IL‐1β and IL‐6 were shown to induce ADAMTS5 expression in osteoarthritis." (PMID 40164572, 2025). "In terms of experimental design, while the IL-1β-induced chondrocyte model effectively mimics key inflammatory aspects of osteoarthritis, it does not fully recapitulate the complexity of native joint tissue, including cell-matrix interactions and mechanical loading." (PMID 41567337, 2025). "In an animal model of osteoarthritis, HMW HA significantly reduced TLR4, TLR2, MyD88, and NF-kB expression in synoviocytes along with reduced mRNA and protein production for several pro-inflammatory molecules (e.g., TNFα, IL-1β, IL-17, MMP-13, inducible nitrous oxide synthase)." (PMID 37107200, 2023). "Previous studies have shown that the PI3K/Akt pathway is closely related to osteoarthritis and that IL-1β can trigger a strong inflammatory response by activating a complex network of signalling pathways, in which PI3K/Akt signalling is closely intertwined with IL-1β-induced inflammation." (PMID 38049841, 2023). "In osteoarthritis (OA), MTT(3-(4,5-dimethyl-2-thiazolyl)-2,5-diphenyl-2-H-tetrazolium bromide, Thiazolyl Blue Tetrazolium Bromide) and flow cytometry as well as western blot data elucidated that IL-1β stimulation inhibited chondrocyte proliferation and promoted apoptosis." (PMID 37372440, 2023).
osteoarthritis (continued). "Results showed that IL-1β increased miR-181a-5p and decreased selenocysteine insertion sequence binding protein 2 (SBP2) in a time- and dose-dependent manner, and miR-181a-5p could be controlled by SBP2 in osteoarthritis to reduce antioxidant properties." (PMID 37587519, 2023). "Also, CEP could reverse the reduced level of cellular autophagy in IL-1β or TNF-α–induced chondrocytes, indicating that the protective effect of CEP on osteoarthritis was achieved by restoring MAPK/NF-κB-mediated autophagy." (PMID 35800437, 2022). "Importantly, our study revealed that FA suppressed MMP‐1, MMP‐3, and MMP‐13 production stimulated by IL‐1β in vitro, suggesting that FA may be effective for restoring ECM composition and structure to halt osteoarthritis progression." (PMID 34078001, 2021). "Finally, Osteoarthritis treatment with IL-1β inhibitors was not fully satisfactory, thus resizing the role of this interleukin in OA pathogenesis." (PMID 33193305, 2020). "However, we detected high concentrations of both FADD and IL-1β in the knee synovial fluid from patients with gout attack, as compared to patients with osteoarthritis (OA), considered as a non-inflammatory rheumatic disease." (PMID 30804327, 2019). "Supporting evidence to a role for IL-1β in osteoarthritis from the CANTOS database is derived from (i) the large number of patients enrolled world-wide, (ii) the randomized, placebo controlled nature of the trial, and (iii) the specificity of IL-1β neutralization." (PMID 30459597, 2018). "As expected, our findings suggest that the anti-inflammatory effects of Guilu Erxian Liquid (GE-L), following marked decrease on both IL-1β and TNF-α during the early course of post-traumatic osteoarthrosis (OA), may be of potential value in the treatment of osteoarthritis." (PMID 30340603, 2018). "Inflammatory cytokines such as interleukin-1 beta (IL-1β), interleukin-6 and tumor necrosis factor-alpha (TNF-α) produced by activated synoviocytes, mononuclear cells or by articular cartilage itself are strongly related to the pathophysiology of osteoarthritis." (PMID 28977876, 2017). "Furthermore, the mediators (IL-1β and IL-6) related to arthrosis were not quantitatively higher in fractured knees." (PMID 26037740, 2015). "Although evidence suggests that short exposure to IL-1β results in minor joint inflammation without permanent joint destruction, continuous exposure to IL-1β results in joint degradation that bears striking resemblance with osteoarthritis." (PMID 24286177, 2013). "Regarding whether Anxa1 exerts joint‐protective effects through TGFβ regulation, some studies have indicated that EVs derived from neutrophils of Anxa1‐deficient mice can inhibit the expression of cartilage degradation factors induced by IL‐1β stimulation in osteoarthritis without relying on Anxa1." (PMID 40125663, 2025). "Studies have shown that levels of inflammatory mediators, such as IL-6, IL-1β, COX-2, and PGE2, undergo significant changes throughout the progression of OA; therefore, attenuating IL-1β-induced inflammation in chondrocytes may offer a potential treatment strategy for osteoarthritis." (PMID 39416781, 2024). "Moreover, IL-1β and TNFα also stimulate the synthesis of prostaglandins, nitric oxide, phosphatidylinositol 3-kinase (PI3K)/protein kinase B (Akt), nuclear factor κB (NF-κB), and diverse mitogen-activated protein kinase (MAPK) signaling pathways further contributing to osteoarthritis pain." (PMID 31905764, 2019). "Interestingly, in a non-inflammatory environment CTS between 12 and 18% mimics the effects of the inflammatory mediator IL-1β and induces similar reactions to those found in osteoarthritis, whereas lower strains were not sufficient to induce anti-inflammatory actions." (PMID 25822615, 2015). "Given the observed enrichment of IL-6 and IL-1β in local lesions, we measured their levels in the circulation of NONFH and osteoarthritis patients." (PMID 35573242, 2022).